PCAT19 (prostate cancer associated transcript 19)
Synonyms: LINC01190; formerly LOC100505495
Gene: Long non-coding RNA gene on chromosome 19 (41,449,520 to 41,502,015, reverse strand). Ensembl gene ENSG00000267107.
Diseases named in the same sentence as PCAT19 in open-access papers:
PCAT19 is named in the same sentence as 28 diseases in open-access papers, as found by Europe PMC text mining. Sharing a sentence is not in itself a finding about the gene and the disease. The quoted sentences say what the papers report.
prostate carcinoma (26 papers, 2019 to 2025). A carcinoma that arises from epithelial cells of the prostate gland. "For example, the variant rs11672691 (G/A), which resides in an intronic enhancer at the lncRNA PCAT19 locus, correlates with prostate cancer predisposition and aggressiveness." (PMID 34449663, 2021). "For example, the risk SNP rs11672691, which is associated with aggressive prostate cancer, mediated the interaction of promoters and enhancers and regulated the expression of lncRNA PCAT19." (PMID 31635067, 2019). "For instance, only the long isoform AS of lncRNA prostate cancer-associated transcript 19 (PCAT19) promotes prostate cancer growth and metastasis by interacting with the heterogeneous nuclear ribonucleoprotein A/B (HNRNPAB) complex, in contrast to its short isoform." (PMID 39724297, 2025). "Furthermore, the SNP rs11672691 is a risk locus associated with prostate cancer that is related to the lncRNA PCAT19." (PMID 36428729, 2022). "Prostate cancer risk-associated SNPs, rs11672691 and rs887391, were identified to regulate two PCAT19 lncRNA isoforms with two distinct transcription start sites, PCAT19-short and PCAT19-long, through a promoter-to-enhancer switching mechanism." (PMID 34946977, 2021). "Recent studies have reported that prostate cancer risk-associated G allele of rs11672691 is associated with an increased expression of lincRNA PCAT19 and oncogene CEACAM21; SNV rs11672691 is located in an enhancer element and may alter the binding site of its oncogenic transcription factor HOXA2." (PMID 32523949, 2020). "For example, LncRNA PCAT19 plays an important role in the snp-mediated promoter-enhancer conversion mechanism in the process of regulating prostate cancer and adjusts the proliferation of laryngeal cancer cells by regulating the miR-182/PDK4 axis." (PMID 35854199, 2023). "highlighted an SNP risk region within the PCAT19 locus that ultimately mediates prostate cancer progression, we have identified a specific role for PCAT19 in the quiescent-proliferative switch of human endothelial cells." (PMID 36384122, 2022). "The risk is determined by the PCAT19-long enhancer interacting with the PCAT19-long promoter, thereby altering prostate cancer development through activating cell cycle genes." (PMID 36428729, 2022). "A risk-associated sequence in the PCAT19-long enhancer interacts with the PCAT19-long promoter to enhance prostate cancer development through activating cell cycle genes." (PMID 36428729, 2022). "The binding of transcription factors NKX3.1 and YY1 to the PCAT19 promoter leads to strong enhancer activity and activation of lncRNA PCAT19, thereby promoting tumor growth and metastasis of prostate cancer." (PMID 36304471, 2022). "For example, the SNP rs11672691, located in the promoter region of lncRNA PCAT19, modulates the function and expression of PCAT19, promoting prostate cancer progression through the upregulation of cell cycle gene expression." (PMID 34249084, 2021). "The risk variant of rs11672691 in lncRNA PCAT19 suppresses binding of transcription factor NKX3.1 to the promoter of PCAT19-short, resulting in PCAT19-long activation and prostate cancer growth and metastasis." (PMID 34336850, 2021). "Among the 12 immune-related lncRNAs, PCAT19 level is downregulated in non-small cell lung carcinoma and regulates the development of prostate cancer." (PMID 34925511, 2021). "More specifically, the risk allele rs11672691-G enhances the binding activity of the novel transcription factor HOXA2, which in turn regulates expression of PCAT19 in prostate cancer through enhancer–promoter loop formation." (PMID 34449663, 2021). "PCAT19 interacts with HNRNPAB to activate a subset of cell-cycle genes associated with prostate cancer progression, thereby promoting prostate cancer tumor growth and metastasis." (PMID 35095999, 2021).
prostate carcinoma (continued). "The lncRNA PCAT19 also interacts with HNRNPAB to activate a subset of cell‐cycle genes associated with prostate cancer progression, thus promoting prostate cancer growth and metastasis." (PMID 32364285, 2020). "CRISPR/Cas9-mediated interference and activation assays have demonstrated that rs11672691 variant is involved in the regulation of its eQTL genes PCAT19 and CEACAM21 expression and affects the cells’ aggressive property in prostate cancers." (PMID 32523949, 2020). "For instance, PCAT1, PVT1, and PCAT19 in prostate cancer, CUPID1 and CUPID2 in breast cancer, PTCSC2 and PTCSC3 in thyroid cancer, LINC00673 in pancreatic cancer, lncPSCA in gastric cancer, as well as LCETRL3 and LCETRL4 in non-small cell lung cancer, are implicated in malignant development." (PMID 37072811, 2023). "Due to the enrichment of PCAT19 in endothelial cells and its previously reported link to prostate cancer, we wondered whether the perturbation of PCAT19 would have an impact on endothelial cell cycle or growth." (PMID 36384122, 2022). "PCAT19-long promoted prostate cancer progression by interacting with a nuclear riboprotein, Heterogeneous Nuclear Ribonucleoprotein A/B (HNRNPAB), to upregulate a subset of cell-cycle genes, suggesting a novel mechanism for the HNRNPAB role in prostate cancer progression." (PMID 34946977, 2021). "CRISPR/Cas9-mediated introduction of single nucleotide mutation was used to directly demonstrate that the presence of allele G led to higher levels of PCAT19 and CEACAM21 transcripts; the genotype of rs11672691 was successfully converted from G/A to G/G or A/A in prostate cancer cell line 22Rv1." (PMID 34208629, 2021). "Interestingly, an additional study discovered a rs11672691-mediated promoter-enhancer switching mechanism driving the expression of lncRNA PCAT19 and thus the initiation and progression of aggressive prostate cancer." (PMID 31013831, 2019). "The presence of additional variants that also reside in the PCAT19 locus plays a crucial role in PCAT19 transcript isoform generation (PCAT19-short and PCAT19-long isoforms respectively) with the PCAT19-long elevated mRNA levels determining progression of prostate cancer." (PMID 34449663, 2021). "A previous study has reported lncRNA PCAT19 rs11672691 suppressed binding of transcription factor NKX3.1 to the promoter of PCAT19-short and lead to prostate cancer progression." (PMID 37217794, 2023). "The SNP, rs11672691, resides in an active enhancer element and the risk G allele increases the chromatin binding of HOXA2, which subsequently promotes the expression of PCAT19 and CEACAM21, which may contribute to the aggressive phenotype of prostate cancer." (PMID 31013831, 2019).
laryngeal carcinoma (8 papers, 2021 to 2024). Carcinoma that arises from the laryngeal epithelium. "Studies have reported that the high expression of PCAT19 in patients with laryngeal cancer is associated with poor overall survival of patients with laryngeal cancer." (PMID 35095999, 2021). "For instance, in laryngeal cancer, PCAT19 is markedly overexpressed in tumor tissues compared to adjacent normal tissues, with higher levels observed in advanced stages (III and IV)." (PMID 39744012, 2024). "Studies also found that PCAT19 contributed to carcinogenesis across other cancer types, including lung carcinoma, larynx carcinoma and glioma." (PMID 36992525, 2023). "By modulating the miR‐182/PDK4 axis, PCAT19 promotes the proliferation of laryngeal carcinoma cells." (PMID 34925511, 2021). "Moreover, PCAT19 can promote the proliferation of laryngeal cancer cells through the miR-182/ PDK4 axis." (PMID 35480331, 2022). "In vitro experiments using laryngeal cancer cell lines HEp-2 and AMC-HN-8 demonstrated that knocking down PCAT19 reduces cell proliferation, enhances mitochondrial respiration, and inhibits glycolysis." (PMID 39744012, 2024). "PCAT19 also acts as a competing endogenous RNA, in which it sponges the miR-182 to regulate the PDK4, and consequently modulates the glycolysis and mitochondrial respiration in laryngeal cancer cell lines." (PMID 35415316, 2022).
lung carcinoma (7 papers, 2020 to 2025). "PCAT19 has been implicated in the pathogenesis and progression of multiple cancers, including glioma, laryngocarcinoma, breast cancer, lung cancer, GC, PCa, and bladder cancer." (PMID 39744012, 2024). "For example, in lung cancer, PCAT19 exhibits high expression in NSCLC tissues compared to adjacent normal tissues, demonstrating strong discriminatory power with a high area under the curve." (PMID 39744012, 2024). "This dual functionality underscores PCAT19’s potential as both a prognostic biomarker and a therapeutic target in lung cancer, providing new avenues for tailored treatment strategies." (PMID 39744012, 2024). "Conversely, PCAT19 is significantly downregulated in breast cancer, lung cancer, colorectal cancer (CRC), and endometrial cancer." (PMID 39744012, 2024). "In lung cancer, overexpression of LncRNA PCAT19 increased apoptosis in cancer cells through miR‐25‐3p/MAP2K4 signaling axis." (PMID 36992525, 2023). "In this study, we observed that PCAT19 was lowly expressed in 11 types of cancers, especially in lung cancer tissues." (PMID 35615401, 2022). "The expression of PCAT19 was detected in lung cancer (LC) tissues and cells by quantitative real-time polymerase chain reaction (qRT-PCR)." (PMID 35615401, 2022). "In addition, PCAT19 regulates the proliferation and apoptosis of lung cancer cells by inhibiting miR-25-3p via targeting the MAP2K4 signal axis." (PMID 39744012, 2024). "Interestingly, PCAT19 lncRNA was predominantly localized in the cytoplasm of various cancer cell types, including lung cancer cells (A549, SK-MES-1) and GC cells (AGS, MGC-803), and highly enriched in the nuclear fraction of PCa cells (LNCaP, V16A)." (PMID 39744012, 2024). "PCAT19 has been studied extensively for its dual roles in lung cancer." (PMID 39744012, 2024). "However, subsequent studies have shown that PCAT19 is significantly downregulated in lung cancer, including NSCLC and lung adenocarcinoma (LUAD)." (PMID 39744012, 2024). "Moreover, the relationship between PCAT19 and lung cancer survival was predicted by using the Kaplan-Meier plotter, and the result uncovered that LC patients with a high expression of PCAT19 had a higher survival rate (P < 0.001)." (PMID 35615401, 2022). "Both PCAT19 and miR-25-3p have been reported in lung cancer studies, but whether there is a correlation between the two and whether they jointly regulate the progress of lung cancer have not been reported yet." (PMID 35615401, 2022).
non-small cell lung carcinoma (7 papers, 2021 to 2024). A group of at least three distinct histological types of lung cancer, including non-small cell squamous cell carcinoma, adenocarcinoma, and large cell carcinoma. "PCAT19 is a novel lncRNA that activates the cell cycle in prostate cancer progression 10, and it promotes the proliferation of laryngocarcinoma and non-small cell lung cancer." (PMID 34976174, 2022). "PCAT19 is significantly down-regulated in non-small cell lung carcinoma and may be involved in its pathogenesis." (PMID 35480331, 2022).
breast carcinoma (4 papers, 2023 to 2025). "Functional assays demonstrated that knocking down PCAT19 in breast cancer cell lines MCF-7 and T47D promoted cell proliferation, while overexpression inhibited tumor growth in vivo." (PMID 39744012, 2024). "This inverse relationship suggests that PCAT19 may act as a protective factor in breast cancer, where its downregulation predicts better OS and DFS." (PMID 39744012, 2024). "In contrast, in breast cancer, PCAT19 expression is notably downregulated." (PMID 39744012, 2024). "This work demonstrated that lncRNA PCAT19 could curb breast cancer development by inhibiting proliferation." (PMID 36992525, 2023). "LncRNA PCAT19 is a potential biomarker of breast cancer and might help to improve precise patient stratification in the future." (PMID 36992525, 2023). "Conversely, in breast cancer and LUAD, PCAT19 exhibits tumor-suppressive properties, inhibiting these cellular processes." (PMID 39744012, 2024). "In situ hybridization (ISH) assays confirmed that PCAT19 expression is lower in breast cancer tissues compared to normal tissues." (PMID 39744012, 2024).
lymph node metastasis (4 papers, 2022 to 2024). "Bioinformatic analyses and machine learning models identified PCAT19 as crucial for prognosis, with high expression levels associated with lower clinical stages and reduced lymph node metastasis." (PMID 39744012, 2024). "In bladder cancer, patients with high PCAT19 expression have significantly lower survival rates and worse prognosis, with notable differences in tumor size, T staging, tumor grade, lymph node metastasis, and distant metastasis." (PMID 39744012, 2024). "Patients with high expression levels of PCAT19 had a lower clinical stage and less lymph node metastasis." (PMID 36992525, 2023). "The PCAT19 expression in GC was significantly related to tumor size, lymph node metastasis, and pathological stage." (PMID 34976174, 2022).
pancreatic cancer (4 papers, 2022 to 2024). "Here, significant upregulation of PCAT19 was observed in acute myeloid leukemia (AML) and pancreatic cancer, reinforcing the potential oncogenic role of PCAT19 in these malignancies." (PMID 39744012, 2024). "PCAT19 could activate cell-cycle genes thereby promoting cancer cell growth and cancer metastasis in pancreatic cancer." (PMID 36467998, 2022).
gastric cancer (3 papers, 2022 to 2024). A primary or metastatic malignant neoplasm involving the stomach. "To investigate if lncRNA contributes to gastric cancer (GC), we conducted a bioinformatics analysis in human microarray datasets, and the results showed that lncRNA prostate cancer-associated transcript 19 (PCAT19) was upregulated in GC." (PMID 34976174, 2022). "Notably, PCAT19 is upregulated in several cancers, including glioma, laryngocarcinoma, gastric cancer (GC), and PCa." (PMID 39744012, 2024).
asthma (2 papers, 2022 to 2023). "As indicated by the ROC analysis, the lncRNA, PCAT19, had high diagnostic accuracy (AUC >0.9) in distinguishing T2 asthma patients from non-T2 asthma patients and healthy controls." (PMID 35480331, 2022). "In this condition, PCAT19-dominated ceRNA regulation systems may have a crucial effect, and PCAT19 may be useful as a possible immune-correlated marker for asthma or other respiratory pathologies associated with eosinophilic inflammation." (PMID 36675299, 2023). "The top five AUCs for DElncRNAs of the T2 asthma and healthy control groups included PCAT19 (AUC = 0.949), TP53TG1 (AUC = 0.876), SNHG16 (AUC = 0.852), LINC01133 (AUC = 0.844), and PP7080 (AUC = 0.827)." (PMID 35480331, 2022). "Notably, the results suggested that PCAT19 achieved the best diagnostic value for distinguishing between the T2 asthma patients from those with non-T2 asthma, and it may serve as a promising biomarker for T2 asthma." (PMID 35480331, 2022). "PCAT19 plays a role in the occurrence and development of various diseases, whereas its role in asthma—especially in the T2 asthma type—remains unclear." (PMID 35480331, 2022). "In T2 asthma, PCAT19-dominated ceRNA regulation networks may play a critical role, and PCAT19 may serve as a potential immune-related biomarker for asthma and other respiratory diseases correlated with eosinophilic inflammation." (PMID 35480331, 2022). "Similarly, the following results showed that the DElncRNAs with the top five AUCs of the T2 asthma and non-T2 asthma groups: PCAT19 (AUC = 0.914), COLCA1 (AUC = 0.827), SLC9A3-AS1 (AUC = 0.824), SNHG16 (AUC = 0.802), and LINC01133 (AUC = 0.793)." (PMID 35480331, 2022). "Moreover, the integrative analysis of this study confirmed the potential of PCAT19 in the diagnosis and classification of asthma." (PMID 35480331, 2022). "Clarifying the pathophysiologic function of PCAT19 in asthma may further increase its clinical significance." (PMID 35480331, 2022). "As revealed by the characteristic cytokine (IL-13/IL-33)-induced T2 asthma cellular model, the expression trend of only four lncRNAs, EPB41L4A-AS1, PCAT19, SLC9A3-AS1, and SNHG16, was consistent with the results of RNA sequencing with the stimulation of IL-13 and IL-33." (PMID 35480331, 2022).
endometrial cancer (2 papers, 2021 to 2024). Primary or metastatic malignant neoplasm involving the endometrium (mucous membrane that lines the endometrial cavity). "In endometrial cancer, PCAT19 is significantly downregulated in cancer tissues, with its expression negatively associated with tumor grade and stage, and lower PCAT19 expression is indicative of shorter OS in endometrial cancer." (PMID 39744012, 2024).
squamous cell carcinoma (2 papers, 2020 to 2022). A carcinoma arising from squamous epithelial cells. "Adenocarcinomas showed a significantly higher expression for PCAT19 (p = 4.14 × 10–18), FENDRR (p = 0.011), LANCL1-AS1 (p = 1.26 × 10–4), LINC00968 (p = 3.97 × 10–12) and ADAMTS9-AS2 (p = 1.92 × 10–44) when compared to squamous cell carcinomas." (PMID 32020063, 2020).
bladder cancer (1 paper, 2024). "PCAT19 is upregulated in bladder cancer tissues and is negatively correlated with miR-335-5p expression." (PMID 39744012, 2024). "Recent research has identified the PCAT19 as a crucial regulator in the malignant progression of bladder cancer through the miR-335-5p/IER2 axis." (PMID 39744012, 2024).
breast tumor (1 paper, 2023). "We further investigated the correlation between expression levels of LncRNA PCAT19 and the clinicopathological details of BC patients, as well as the mechanisms underlying the breast tumor‐inhibiting ability of PCAT19." (PMID 36992525, 2023).
glioma (1 paper, 2024). A benign or malignant brain and spinal cord tumor that arises from glial cells (astrocytes, oligodendrocytes, ependymal cells). "PCAT19 is significantly upregulated in glioma tissues, where it acts as a molecular sponge for miR-142-5p, which has been reported to facilitate cell communication and can affect cancer cell behaviors in multiple tumors." (PMID 39744012, 2024). "For instance, in glioma, laryngocarcinoma, and GC, PCAT19 functions as an oncogene, promoting cell proliferation, migration, and invasion by interacting with various miRNAs and signaling pathways." (PMID 39744012, 2024). "Recent research has highlighted the critical role of the PCAT19 in glioma progression." (PMID 39744012, 2024). "In vitro experiments have demonstrated that knockdown of PCAT19 or overexpression of miR-142-5p decreases glioma cell proliferation, colony formation, and invasion, while promoting apoptosis by modulating the expression of Cyclin B1, CDK2, N-cadherin, Bcl-2, Bax, and E-cadherin." (PMID 39744012, 2024). "Additionally, in vivo studies using glioma xenograft models have shown that silencing PCAT19 significantly reduces tumor growth." (PMID 39744012, 2024).